IL7 (interleukin 7)
Diseases named in the same sentence as IL7 in open-access papers (continued):
Sharing a sentence is not in itself a finding about the gene and the disease.
influenza (17 papers, 2012 to 2025). An acute viral infection of the respiratory tract, occurring in isolated cases, in epidemics, or in pandemics; it is caused by serologically different strains of viruses (influenzaviruses) designated A, B, and C, has a 3-day incubation period, and usually lasts for 3 to 10 days. "Using IL-7Rα signaling deficient mice, we show that IL-7 is required for a normal sized mediastinal lymph node and the early clonal expansion of influenza-specific CD8 T cells therein." (PMID 34997007, 2022). "We had previously shown that IL-7 signaling deficient mice have reduced accumulation of influenza-specific CD8 T cells following influenza infection." (PMID 34997007, 2022). "To assess the importance of IL-7 signaling in CD8 T cells following infection with influenza, we used mice expressing a mutated IL-7Rα whereby a cytoplasmic tyrosine important for signal transduction is substituted to a phenylalanine at residue 449 (IL-7Rα449F)." (PMID 34997007, 2022). "Animal studies have shown that IL-7 is required for the optimal response to acute influenza infection, since it shapes the early priming of CD8 cytotoxic T cells." (PMID 39903535, 2025). "The top genes with a negative interaction (meaning being less up-regulated than expected in mice exposed to HDM and influenza compared to either exposure alone) included genes involved in Th1 development, such as Ms4a4b, Oas1h, and Il7, and many others." (PMID 40331962, 2025). "Striking reactivities were observed particularly for IFN-α8, IFN-γ, IL-6, IL-7, IL-12p70, and IL-22, while serum from 1 patient with influenza showed high MFI levels for both GM-CSF and soluble RANK ligand." (PMID 36752204, 2023). "We found that IL-7 expression is induced within 24 h following influenza infection correlating with the antiviral response signified by IFN-β and viral replication demonstrated by M1 mRNA transcript expression." (PMID 34997007, 2022). "To assess IL-7 expression dynamics in response to influenza, we first infected human type II epithelial cells (A549) with influenza and assessed Il7 mRNA using qRT-PCR." (PMID 34997007, 2022). "Our findings show that IL-7 is intrinsically important for the accumulation of influenza-specific CD8 T cells during early priming phase in the mdLN independent of TCR specificity and the number of naïve T cell precursors." (PMID 34997007, 2022). "In summary, we have found that IL-7 is required for an optimal response to acute influenza infection as it shapes the early priming stages of CD8 T cells." (PMID 34997007, 2022). "It is possible a low dose, local influenza infection recapitulates the low level TCR stimulation model whereby IL-7 plays an essential role in CD8 T cells under low TCR avidity activation." (PMID 34997007, 2022). "In TIL obtained from patient without MPR MD01-004, culture with titrating concentrations of IL-7 in vitro induced much higher levels of IL-7R-regulated genes in influenza-specific TIL than in MANA-specific TIL." (PMID 34290408, 2021). "MANA-specific CD8 T cells have hallmark transcriptional programs of tissue-resident memory (TRM) cells, but low levels of interleukin-7 receptor (IL-7R) and are functionally less responsive to interleukin-7 (IL-7) compared with influenza-specific TRM cells." (PMID 34290408, 2021). "IL-7 was shown to be a useful adjuvant for vaccination as influenza-specific vaccine antibody responses were efficiently boosted by IL-7 through increased Tfh cell numbers in lymph nodes." (PMID 28473831, 2017). "This is in concert with animal studies demonstrating that IL-7-treated old macaques with increased TREC levels responded better to inactivated influenza vaccine, with stronger influenza antigen-specific proliferative response and higher HAI titers." (PMID 25816015, 2015). "We cultured PBMC in vitro in the presence of RA9 peptide-pulsed autologous PMBCs, IL-7 and IL-2 from three influenza vaccinated animals (B0527, 19351 and B0547) at day 91 post initial vaccination." (PMID 22403659, 2012).
influenza (continued). "We also showed that IL-7 signaling was necessary for the generation of a robust influenza A-specific CD4 and CD8 T cell response and that this requirement is intrinsic to CD8 T cells." (PMID 23189186, 2012). "Prophylactic administration of IL-7 protects against lethal influenza in a murine model." (PMID 39903535, 2025). "Interestingly, IL-7-boosted Tfh and GC B cell reactions induce both influenza vaccine-specific IgG1 and IgG2c production, which conflicts with our finding that TSLP preferentially induces IgG1 rather than IgG2c responses." (PMID 40035515, 2025). "However, following infection with influenza, IL-7-eGFP+ epithelial cells (ECs) and to a lesser extent stromal cells (SCs) expanded while LECs decreased in frequency." (PMID 34997007, 2022). "Adjuvant effects of IL-7 have been studied in the vaccines of influenza and other pathogens." (PMID 33562631, 2021). "For example, our data demonstrated reduced activation of transcriptional programs downstream of IL-7 ligation in MANA-specific TIL relative to influenza-specific TIL, but the MANA-specific TIL retain their ability to respond to supraphysiological levels of IL-7." (PMID 34290408, 2021). "We show that in the lung draining mediastinal LNs (mdLNs), IL-7 is important for early priming and accumulation of CD8 T cells specific for influenza NP366–374 and PA224–233 presented on H2Db in a cell intrinsic manner." (PMID 34997007, 2022). "MANA-specific T cells also express far less IL-7R relative to influenza TRM, translating functionally into poor IL-7 responsiveness." (PMID 34290408, 2021). "The cooperation of these two signaling pathways (IL-7 and IL-15 signaling) supported the residence of CD4+ TSCMs in the bone marrow and the recalling of CD4+ TSCMs in the influenza model." (PMID 30733641, 2019). "This suggest that the antibody response to H. polygyrus, but not Influenza/A, is dependent on IL-7 signaling through IL-7Rα Tyr449." (PMID 24551160, 2014). "IL-7 and IL-15 are critical for memory CD8+ T-cell homeostasis 9–11, and expression of IL-7R and IL-15R by NP-specific CD8+ T cells was comparable at 2 and 6 months after influenza infection." (PMID 22965681, 2012). "Therefore, it is possible that the reduction in influenza-specific CD8 T cell accumulation was due to factors extrinsic to T cells in the lymph node and that IL-7 was indirectly important for shaping the cellular and cytokine environment for optimal T cell activation." (PMID 34997007, 2022). "In addition, specific influenza vaccine antibody responses were efficiently boosted by IL-7, which acted by increasing Tfh cell frequency in lymph nodes; this IL-7 effect was specific for Tfh cells and did not affect other types of T helper cells." (PMID 28473831, 2017). "Additionally, SARS-CoV-2 can increase pro-inflammatory cytokines, including interleukin (IL)-2, IL-6, IL-7, and tumor necrosis factor-alpha (TNF-a), to levels not typically seen in bacterial sepsis or influenza and contribute to thrombosis formation via multiple mechanisms." (PMID 38903348, 2024).
colon carcinoma (16 papers, 2012 to 2025). "A total of 15 differentially expressed interleukins between the colon cancer tissue and normal colon tissue were evaluated from the Cancer Genome Atlas (TCGA) database with R software and only interleukin-7 (IL-7) was significantly associated with survival." (PMID 32381120, 2020). "For further exploration of IL-7 expression in clinical colon cancer patients, Western Blotting and IHC were performed." (PMID 32381120, 2020). "IL-7 was a key factor in inhibiting the progression of colon cancer and was closely related to overall survival." (PMID 32381120, 2020). "As expected, IL-7 protein was significantly decreased in early stage colon cancer compared with paired normal tissue, meanwhile the expression of IL-7 in advanced stage colon cancer showed further decrease." (PMID 32381120, 2020). "As predicted in GSEA analysis above, we inferred IL-7 promotes apoptosis of colon cancer to repress its progression." (PMID 32381120, 2020). "We finally verified the expression of IL-7 in clinical patients and found that IL-7 was significantly down-expressed in colon cancer tissues compared to normal tissues." (PMID 32381120, 2020). "We finally found that interleukin 7 was significantly down-regulated in colon cancer compared with normal tissue." (PMID 32381120, 2020). "Further analysis of IL-7 expression with clinical data indicated that IL-7 was a key factor in inhibiting colon cancer progression." (PMID 32381120, 2020). "Concerning colon cancer, IL-7 was evaluated in single-cell suspensions derived from patients, in human colon carcinoma xenografts, and mouse models of peritoneal and lung metastasis." (PMID 31185636, 2019). "Studies on the IL-7 effect on colon-cancer cells yielded consistent results, showing that IL-7 alone had neither a positive nor a negative effect on tumors." (PMID 31185636, 2019). "Of these, six mRNA including ECM1, GZMB, KLK10, CCL20, MMP9, and IL7 have been previously reported to have a prognostic role in colon cancer." (PMID 29377588, 2018). "Experimental immunodeficient tumor-bearing mice have provided the evidence of the anti-tumor properties of recombinant human IL-7 (rhIL-7) on a human colon tumor." (PMID 24551818, 2014). "Utilizing lung and abdomen metastasis models by inoculation of CT26 mice colon cancer cells, we evaluated the anti-tumor efficacy of combining IL-7 and OXP in mice models." (PMID 24465710, 2014). "Our study shows that the OXP plus IL-7 combination treatment significantly inhibited tumor growth in murine models of colon cancer." (PMID 24465710, 2014). "Besides, in vivo administration of IL-7 in combination with oxaliplatin was found to remarkably inhibit the growth of tumors in lung and abdominal metastasis models of colon cancer by reactivating the immune system." (PMID 31915416, 2019). "We evaluated the anti-tumor activity of IL-7 combining OXP against a murine colon carcinoma in vitro and in vivo and studied the tumor immune microenvironment to investigate whether the combined treatment affects on the local immune cell populations." (PMID 24465710, 2014). "However, OXP combined with IL-7 significantly inhibited tumor growth in murine models of colon cancer." (PMID 24465710, 2014). "The study demonstrated that IL-7 could inhibit the progression of colon cancer." (PMID 32381120, 2020). "IL-7 may inhibit the development of colon cancer cells through apoptotic pathway." (PMID 32381120, 2020). "In our study, we evaluated the antitumor activity of IL-7 combined with OXP against a murine colon carcinoma in vitro and in vivo and examined the tumor immune microenvironment to investigate whether this combined treatment affects local immune cell populations." (PMID 24465710, 2014).
colon carcinoma (continued). "In addition, vaccination of patients with progressive colon cancer disease with autologous tumor cells transfected with IL-7 and GM-CSF genes could result in regression of tumor in some patients." (PMID 24551818, 2014). "To explore how IL-7 was involved in colon cancer progression, we performed a GSEA based on the TCGA colon cancer cohort." (PMID 32381120, 2020). "Our study showed that the in vivo administration of IL-7 combined with OXP markedly inhibited the growth of tumors in lung and abdomen metastasis models of colon cancer." (PMID 24465710, 2014). "In the lung metastasis model, we found that combination-treated CT26 colon tumor bearing mice had a lower percentage of Treg cells amongst CD4+ T cells in the spleen, in comparison with IL-7 alone, OXP alone, and control mice (P<0.05)." (PMID 24465710, 2014). "For instance, Hombach and colleagues demonstrated that co-administration of mesenchymal stem cells (MSCs) genetically engineered to secrete IL-7 and IL-12 significantly improved the anti-tumor activity of CEA-targeted CAR T cells in a preclinical model of colon cancer." (PMID 40808942, 2025). "On the contrary, we found a negative correlation between HHLA2 tumor concentration factor 1 from principal component analysis containing: HGF, M-CSF, b-NGF, SCGF-b, IL-7, FGFbasic, G-CSF, PDGF-bb, VEGF, GM-CSF, and trophic factors, which can be produced by colon tumor cells." (PMID 36982953, 2023). "In another research focused on the role of IL-7 in the progression of colon cancer, the apoptosis of tumor cells treated with combination of OXP and IL-7 was significantly increased, indicating that IL-7 combined with OXP can significantly reduce cell proliferation and induce apoptosis in vivo." (PMID 32381120, 2020). "We therefore determined whether IL-7, and/or OXP treatment enhanced the presence of activated CD8+ T cells (CD8+CD69+ population) in the two models murine colon tumors." (PMID 24465710, 2014).
malaria (16 papers, 2011 to 2024). Malaria is a serious and sometimes fatal disease caused by a parasite that commonly infects a certain type of mosquito which feeds on humans. "This clinical malaria control is also associated with increased IL-7, IL-10, IL-17, and IL-27 plasma levels as well as IgG and better parasite clearance." (PMID 36293524, 2022). "This study presents the first report on the association between genotypes and haplotypes of IL7 (72194 T/C and -2440A/G) and disease outcomes in children with severe malaria: profoundly low Hb levels and inefficient erythropoiesis." (PMID 31420016, 2019). "Our study is the first large-scale attempt to determine the genetic basis of placental infection in malaria, and suggests an important unexpected role of the IL-7/IL-7R pathway for the susceptibility of this important clinical condition." (PMID 21949827, 2011). "To date, only one study has reported an association between IL7 genetic variation and malaria." (PMID 31420016, 2019). "Based on the potentially important role of IL-7 in malaria, results presented here examined the relationship between two IL7 variants identified in the pilot genomic wide experiment (72194 T/C, rs2583759 and − 2440 A/G, rs7007634) and susceptibility to SMA in Kenyan children." (PMID 31420016, 2019). "A role for IL-7 in malaria is also suggested by studies in murine models in which malarial anemia was associated with suppression of erythropoietic-related cytokines [i.e., granulocyte colony stimulating factor (G-CSF), GM-CSF, IL-7, and IL-17], and elevation of IL-10 and TNF-α." (PMID 31420016, 2019). "In contrast, those with low exposure to malaria had higher interleukin 7 (IL-7) and transforming growth factor β1 (TGF-β1) levels." (PMID 38646476, 2024). "Increased TNF, IFN-γ, IL-6, IL-10, IL-17, CCL2, and CCL3 levels and decreased IL-7 levels were observed in malaria monoinfection compared to dengue virus monoinfection." (PMID 36716305, 2023). "IL-6, IL-13, TNF-α, and IFN-γ were significantly higher in severe malaria, while IL-7, IL-10, IL-17, and IL-27 showed the opposite trend." (PMID 36293524, 2022). "The subgroup IL-15, IL-17 and IL-4 was negatively correlated to the cohort containing IL-6, IL-1Ra MIP-1β, IL-7 and IP-10, which, interestingly, has been shown to be a marker for different infections including malaria and dengue fever." (PMID 34299123, 2021). "For IL7 (72194 T/C) there were 391 participants inheriting the homozygous wild type genotype (TT), of which 318 (81.30%) had UM (uncomplicated malaria), while 73 (18.70%) were in the SMA group." (PMID 31420016, 2019). "In the present study, plasma levels of IL-4, IL-7, IL-12p70, and IL-13 were more elevated in subjects purely with dengue fever than in those with malaria mono-infection or malaria and dengue co-infection." (PMID 26271921, 2015). "It was found that HB and HT displayed several negative significant interactions mainly with IL-4, IL-5, IL-12p70, and IL-17, whereas ALT interacted negatively with IL-4 and IL-7 in the malaria group." (PMID 26271921, 2015). "In the group of patients with malaria and dengue co-infection, HB and HT displayed negative associations with IL-7, whereas AST exhibited positive interactions with CCL2, IL-13 and IL-8." (PMID 26271921, 2015). "Circulating concentrations of IL-4, IL-5, and IL-7 differed across the groups (P < 0.001 for all) and were significantly elevated in the G[+] and G[−] coinfected children, relative to both children with malaria-only (P < 0.001 for all) and healthy controls (P ≤ 0.024 for all), respectively." (PMID 27418744, 2016). "For malaria and virus coinfections, increased TNF, IFN-γ, IL-6, and CCL4 levels and decreased IL-4, IL-7, IL-12, TGF-β, and CCL3 levels were observed in malaria coinfections compared to dengue monoinfection." (PMID 36716305, 2023).
malaria (continued). "Malaria coinfections with bacteremia were characterized by distinct cytokine profiles, including elevated IFN-γ, IFN-α, IL-4, IL-7, IL-12, IL-15, and IL-17 levels and decreased TNF levels, indicating a strong cytokine response." (PMID 36716305, 2023). "Network analyses revealed that cases of malaria and dengue co-infection exhibit a unique immune profile with a special role for TNF, IL-6, IFN-γ, and IL-7." (PMID 26271921, 2015). "In addition, both coinfected groups had increased IL-4, IL-5, IL-7, IL-12, IL-15, IL-17, IFN-γ, and IFN-α and decreased TNF-α relative to malaria alone." (PMID 27418744, 2016). "The group of malaria mono-infected patients exhibited a biosignature composed by higher levels of IL-10 and CCL2 whereas the group of dengue mono-infected individuals displayed a signature with high expression of IL-4, IL-7 and Il-12 in plasma." (PMID 26271921, 2015). "In a mouse model of malaria using P. berghei, the parasite ortholog of macrophage migration inhibitory factor (PMIF) induced the upregulation of T-bet and IFN-γ and the downregulation of IL-7R, IL-7, IL-2 and Bcl-2 in T cells specific for the parasite." (PMID 25559491, 2015). "However, of these, only IL-12 was directly associated to previous episodes of malaria in the multivariate analysis; to our knowledge, there is no data in the literature on the influence of P. falciparum infection or malaria interventions in the concentrations of IL-7 or G-CSF in peripheral blood." (PMID 22280502, 2012). "However, for the malaria group, four distinct correlation patterns were observed; first pattern (CCL4, CCL2, CCL3, IL12 and IL2), second pattern (IL-17A, IL-1β, CCL11, IL4), third pattern (IL5, IL7, IL13), and fourth pattern (IL1RA, CXCL10, TNFα, IL2R, CXCL9, IL6)." (PMID 35811678, 2022). "However, a potential role for HB and HT in regulation of the inflammatory environment in malaria and dengue comorbidity could not be entirely discarded, and the network findings indicate that these parameters were negatively correlated with IL-7 in this group." (PMID 26271921, 2015). "In the context of laboratory and immune markers correlations, the group of individuals presenting with malaria mono-infection displayed significant negative correlations between ALT and IL-4 and IL-7." (PMID 26271921, 2015).